IL10 (interleukin 10)
Diseases named in the same sentence as IL10 in open-access papers (continued):
Sharing a sentence is not in itself a finding about the gene and the disease.
hyperferritinemia (11 papers, 2013 to 2026). "Active ferritin production by macrophages and cytokines causes hyperferritinemia, resulting in the increase of several proinflammatory (IL‐1) and anti‐inflammatory (IL‐10) cytokines." (PMID 34042296, 2021). "Persistent extreme hyperferritinemia (peak >15,000 ng/mL), markedly elevated LDH (735 U/L), and strikingly high IL-10 (>600 pg./mL) formed a diagnostic triad raising suspicion for IVLBCL." (PMID 42110423, 2026). "For instance, patients receiving high doses of IL10 developed hyperferritinemia whereas iron supplementation in IL10- knock out mouse increased pro-inflammatory cytokine production in high iron diet group compared with chow diet." (PMID 23941335, 2013). "In this patient, the constellation of laboratory findings—including extreme hyperferritinemia, elevated inflammatory cytokines (IL-6, IL-10, TNF-α, IFN-γ), and multi-organ involvement—supports the presence of a cytokine storm or secondary HLH phenotype triggered by influenza A infection." (PMID 41245251, 2025). "Therefore, cut-off values of IL-6, IL-8, and IL-10 for hyperferritinemia were calculated from the receiver operating characteristic curve." (PMID 24800252, 2014). "The authors suggested that hyperferritinemia may result from direct stimulation of ferritin translation by IL10 via the suppression of the binding affinity of iron regulatory proteins to the 5’-untranslated region of ferritin mRNA in human monocytic cells." (PMID 23941335, 2013). "Indeed, in addition to significantly reducing the serum levels of IL-6 and C-reactive protein (CRP), ruxolitinib could influence the regulation of several inflammatory cytokines (including IL-2, IL-5, and IL-10), and consequently reduce hyperferritinemia." (PMID 33489899, 2020). "IL-10 and IFN-γ also stimulate iron uptake into macrophages via transferrin receptors or via divalent metal transporter-1, resulting in iron retention and storage in macrophages, which manifests as hyperferritinemia." (PMID 24800252, 2014).
hyperlipidemia (11 papers, 2020 to 2024). "In hyperlipidemia, IL‐1β, IL‐6, IL‐8, and IL‐10 still had significant differences between the SAP group and non‐SAP group (p < .05), while IL‐5, IL‐17, TNF‐α had no statistical differences between the two groups." (PMID 38411379, 2024). "Oral administration of SVP in T2DM mice also could improve the diabetic complications of hyperlipidemia and inflammation response, indicating as lower concentrations of TC, TG, LDL-c, FFA, TBA, TNF-α, IL-6, and higher levels of IL-10 in serum." (PMID 36337615, 2022). "This showed that XOS increased the level of anti-inflammatory factor IL-10 and reduced the levels of pro-inflammatory factors TNF-α, IFN-γ, and IL-6 in the serum, thus exerting a regulatory effect on the blood lipid levels of mice with hyperlipidemia." (PMID 34880767, 2021).
intrauterine growth restriction (11 papers, 2012 to 2024). "The offspring of IL-10−/− mice are also susceptible to uterine NK cell-mediated fetal resorption, intrauterine growth restriction, or preterm birth when exposed to low doses of intraperitoneal LPS." (PMID 37747229, 2023). "Our published observations showed that exposure to A-1254 caused preterm birth, fetal growth restriction, and amniotic fluid increase in IL-10−/− mice." (PMID 28071720, 2017). "Although incidence of preterm birth was reduced, IL-10 treatment also corresponded with intrauterine growth restriction in both infected and mock-infected groups." (PMID 39484515, 2024). "In particular, we have shown that exposure to environmental toxicants such as polychlorinated biphenyls (PCBs) result in preterm birth, intrauterine growth restriction and two-fold increase in amniotic fluid volume only in IL-10−/− pregnant mice." (PMID 28526846, 2017). "Other results have described decreased placental IL-10 production in the decidual region and the trophoblast in pregnancies that are complicated by intrauterine growth restriction, and this has been confirmed in experimental mice studies." (PMID 22462002, 2012). "IL-10 could rescue intrauterine growth restriction and proteinuria in IL-10−/− mice." (PMID 23028860, 2012). "Some studies report decreased plasma IL-10 concentrations with PTB compared to term, whereas others have found an association between elevated plasma IL-10 with an increased risk of pre-eclampsia or intrauterine growth restriction, which may in turn lead to PTB." (PMID 25741339, 2015).
invasive carcinoma (11 papers, 2007 to 2025). A carcinoma that is not confined to the epithelium, and has spread to the surrounding stroma. "al (2012) demonstrated the involvement of E. coli NC101 strain in the progression of invasive carcinoma in azoxymethane (AOM)-treated Il10(-/-) mice." (PMID 34729122, 2021). "Releasereached a maximum for IL-10 and IL-4 in patients with CIN III and decreasedsignificantly for both cytokines in patients with invasive carcinoma.(K. W. test: P=.019 for IL-10 and P=.033 for IL-4)." (PMID 18288269, 2007). "The E. coli pks+ strain promoted invasive carcinoma in an azoxymethane (AOM)-treated IL-10−/− mouse model, while the deletion of the pks genotoxic island from the same strain decreased tumour multiplicity and invasion in AOM/IL10−/− mice." (PMID 33937029, 2021). "Seven of eight (88%) of tumor bearing AOM/Il10−/− mice developed high-grade or invasive carcinoma while none of the 3 tumors observed in WT mice showed evidence of advanced histological stage." (PMID 19551144, 2009).
juvenile idiopathic arthritis (11 papers, 2012 to 2024). Juvenile idiopathic arthritis (JIA) is the term used to describe a group of inflammatory articular disorders of unknown cause that begin before the age of 16 and last over 6 weeks. "In these studies, the ATA haplotype was accompanied by low IL-10 expression in patients with juvenile rheumatoid arthritis and patients undergoing elective cardiopulmonary bypass surgery." (PMID 39199367, 2024). "Previous studies have also shown that the IL-10 ATA haplotype (minor alleles of rs1800896, rs1800871, and rs1800872) was associated with the reduced production of IL-10 in human whole blood cultures of patients with juvenile arthritis." (PMID 39125893, 2024). "However, juvenile rheumatoid arthritis patients homozygous for the GCC haplotype in the promoter region of the IL-10 gene have less disease severity and show 50% higher IL-10 production in blood following LPS stimulation compared to the ATA haplotype." (PMID 28287415, 2017).
Lyme disease (11 papers, 2010 to 2025). Lyme disease (named after the towns in the USA where the disease was first identified) is a bacterial infection caused by Borrelia burgdorferi. "The Lyme disease-resistant C57 mouse has a genetic predisposition to a diminished innate inflammatory response with IL-10 being a key facilitator of this process." (PMID 23024745, 2012). "Inflammatory mediators that are induced by B. burgdorferi (or its lipoproteins) in cells from mice of Lyme disease-resistant and -susceptible strains have been shown to be tightly regulated by the anti-inflammatory cytokine IL-10." (PMID 23024745, 2012). "How IL-10 mediates its anti-inflammatory effects in macrophages of the Lyme disease-resistant and disease-susceptible mouse strains is the topic of our ongoing investigations." (PMID 23024745, 2012). "Genetic susceptibility to Lyme disease in the C3H mouse is here substantiated by its poor ability to regulate innate inflammatory responses, in part because of suboptimal endogenously produced IL-10." (PMID 23024745, 2012). "Our findings, coupled with the more effective host defense in IL-10 deficient mice, suggest that IL-10 production by innate immune cells may dictate the outcome of infection and disease severity in the mouse model of Lyme disease, especially in the disease-resistant C57 mouse, and perhaps in humans." (PMID 23024745, 2012). "Borrelia burgdorferi infection induces a mix of type 1 and type 17 inflammatory as well as regulatory IL-10 responses from canine and human cells (37, –, 41)." (PMID 40741972, 2025). "An antagonistic role has been documented between IL-17 and IL-10 in Lyme borreliosis, and the role of IL-10 in Borrelia infection has been defined as aiding in dissemination." (PMID 35924250, 2022). "We therefore wanted to know to what degree IL-10-mediated suppression of miR-155 contributed to its role as an immune suppressor (miR-155-dependent), versus other (miR-155-independent) effects on Lyme disease pathogenesis." (PMID 26252010, 2015). "In this study, we explored how one such regulatory network, IL-10-mediated regulation of miR-155, influences Lyme disease pathogenesis, immune activation, and host defense during infection with B. burgdorferi." (PMID 26252010, 2015). "Our goal is to delineate which APC immune functions are dysregulated by Bb-elicited IL-10 using a murine model of Lyme disease." (PMID 24367705, 2013). "The anti-inflammatory cytokine IL-10 is known to play a significant role in the development of Lyme disease." (PMID 24367705, 2013). "Inflammatory mediators induced by live Bb or L-OspA were similarly down-regulated by IL-10 in the two mouse strains, suggesting the ability of exogenous IL-10 to regulate inflammation in Lyme disease." (PMID 23024745, 2012). "Our observation further provides compelling evidence, and supports the notion that IL-10 is a potent regulator of inflammatory mediators in BMDM of the Lyme disease-resistant mouse strain." (PMID 23024745, 2012). "In vivo studies using IL-10-/- mice of both C57 and C3H genetic backgrounds underscored the significance of IL-10 in controlling joint inflammation in Lyme disease." (PMID 23024745, 2012). "The anti-inflammatory effect of IL-10 in Lyme disease is well established both by experiments in vitro using various cell types and different B. burgdorferi stimulants as well as in vivo." (PMID 23024745, 2012). "The transcript levels of several important cytokines and chemokines that have been reported to contribute to Lyme disease progression, such as IL-10, IL-1β, TNF-α, and CCL2, were upregulated in the WT- but not MT-infected tissues, which was validated by qRT-PCR." (PMID 38011206, 2023). "Together, these experiments suggest that the suppression of these co-stimulatory molecules on APCs by Bb-elicited IL-10 may contribute to the dysregulated adaptive responses generated during the development of Lyme disease." (PMID 24367705, 2013).
Lyme disease (continued). "A previous study on borrelial infection has shown that IL-10 is differentially expressed in macrophages from different murine models, suggesting that it may contribute to the control of inflammation in Lyme disease." (PMID 24130911, 2013). "Further studies are needed to determine whether treatments aimed at blocking these IL-10 effects can promote efficient clearance of these bacteria in both acute and chronic cases of Lyme disease." (PMID 24367705, 2013). "In Lyme disease, caused by Borrelia burgdorferi, which can suppress TH1 responses to persist in the host, cimetidine may enhance TH1-associated cytokines (IL-12, TNF-α, IFN-γ) and suppress TH2 cytokines (IL-10), restoring immune balance." (PMID 39937247, 2025). "Thus, Bb-elicited IL-10 may play a major role in the dysregulated inflammatory response observed early in the development in Lyme disease and may increase the chances of Bb to evade clearance by the cellular responses and subsequent dissemination to distant tissues." (PMID 24367705, 2013). "Bulk RNA-seq analysis of infected mouse skin tissues further show that cheA1mut fails to elicit mouse tnf-α, il-10, il-1β, and ccl2 expression, four important cytokines for Lyme disease development and B. burgdorferi transmigration." (PMID 38011206, 2023).
necrotizing enterocolitis (11 papers, 2011 to 2026). Necrotizing enterocolitis (NEC) is a devastating disease that affects mostly the intestine of premature infants. "PSA exerts potent anti-inflammatory effects by inducing IL-10 production and preventing inflammation-associated diseases such as necrotizing enterocolitis (NEC), EAE, IBD, and colitis induced by Helicobacter hepaticus." (PMID 40810484, 2025). "Previous research has demonstrated that the exogenous administration of AI-2 contributes to a reduction in intestinal TNF-α and an increase in IL-10, resulting in the attenuation of the inflammatory responses in mice with necrotizing enterocolitis (NEC)." (PMID 38369503, 2024). "Also, plasma levels of cytokines like IL-6, IL-8/CXCL8, and IL-10, among others, are elevated during necrotizing enterocolitis." (PMID 39456833, 2024). "Necrotizing enterocolitis induced in rats can be reversed by human breast milk as well as IL-10, and increased cytoplasmic IL-10 levels in epithelial cells in rats correlated with protection to NEC." (PMID 21464967, 2011). "The CRP, IL-6, IL-10, and IFN-γ in the serum of Necrotizing enterocolitis (NEC) intestinal stenosis patients were significantly higher than the reference values." (PMID 35958178, 2022). "Symptoms of necrotizing enterocolitis (NEC) were associated with elevated levels of IL-6, while the development of cerebral intraventricular hemorrhage in neonates correlated with high CXCL-5 (p = 0.037) and sepsis was associated with high IL-10 levels (p = 0.02)." (PMID 40244141, 2025). "Recent research has also shown that SFN (20 mg/kg/day) mitigates necrotizing enterocolitis (NEC) by reducing the expression of IL-1β, IL-8, IL-10, IL-6, and TNF-α, thereby decreasing apoptosis in NEC-induced mice." (PMID 38671854, 2024).
pneumonitis (11 papers, 2005 to 2025). An inflammatory process affecting the lung parenchyma. "This has prompted the study of early circulatory markers as predictive assays and has revealed associations of serum interleukins (Il6, Il1a, Il8, Il10) with pneumonitis." (PMID 25889053, 2015). "G-1082A SNP of the IL-10 has been associated with a more severe form of pneumonitis." (PMID 39768405, 2024). "However, the role of IL-5 and IL-10 in lung injury associated with pneumonitis remains uncertain." (PMID 40963607, 2025). "Smoking history (p = 0.006), IL-10 (p = 0.017), and IL-12 (p = 0.009) were found have significance in distinguishing the occurrence of pneumonitis." (PMID 35222434, 2022). "Univariate and multivariate logistic regression analyses were utilized, and IL-10 (OR = 9.969, 95% CI 1.144-86.843, p = 0.037) was credible and independently related to the occurrence of pneumonitis." (PMID 35222434, 2022). "When pneumonitis, the most common irAEs, was analyzed, only baseline high-expression IL-10 was accompanied with the incidence of pneumonitis (OR = 9.969, 95% CI 1.144–86.843, p = 0.037)." (PMID 35222434, 2022). "With regard to pneumonitis as the most frequent event among these irAEs, the baseline level of IL-10 plays a reliable role (OR = 9.969, p = 0.037) in predicting the incidence." (PMID 35222434, 2022). "Further to interferonγ and interleukin-17, there was more interleukin 1β and interleukin 10 in the lavage of mice which would later succumb to pneumonitis alone compared to those succumbing to pneumonitis with fibrosis." (PMID 25889053, 2015). "Similarly, interleukin 10 is considered anti-inflammatory thus higher levels of this cytokine in strains developing the inflammatory response of pneumonitis would be unexpected." (PMID 25889053, 2015). "The mRNAs detected were for cytokines involved in acute inflammation and the fibrosis of pneumonitis: TNF-α/β, IL-6, IFN-β/γ, IL-6, IL-10, IL-1α/β, IL12 and MIF." (PMID 16336675, 2005).
rheumatic diseases (11 papers, 2010 to 2025). "Malic acid dependently decreases the content of tumor necrosis factor alpha (TNF-α), interferon γ (IFN-γ), and interleukins 6 (IL6) and IL10; besides, it reduces symptoms in rheumatic diseases." (PMID 40006847, 2025). "Interleukin-10 (IL-10) is an important cytokine with anti-inflammatory properties that have been found at high serum levels in RP secondary to rheumatic disease." (PMID 38743488, 2024). "Exercise also inhibited TNF expression in rheumatic diseases by stimulating muscle production of interleukin-6 (IL-6) and by promoting the production of interleukin-1 receptor antagonist (IL-1Ra), and interleukin-10 (IL-10)." (PMID 31681001, 2019). "Adiponectin the second adipokine most evaluated in rheumatic diseases possesses a complex role with some anti-inflammatory effects as well as inhibition of TNF-α and IL-6 production and the induction of IL-10 synthesis." (PMID 28898254, 2017). "The effect of rheumatism in the JWFSN-middle and JWFSN-high dose groups is particularly obvious, suggesting that the therapeutic effect of JWFSN on CIA rats may be through direct or indirect reduction of TNF-α, IFN-γ, and IL-1β expression and improve IL-4 and IL-10." (PMID 31929822, 2019).